CD274 (CD274 molecule)
Diseases named in the same sentence as CD274 in open-access papers (continued):
Sharing a sentence is not in itself a finding about the gene and the disease.
lung adenocarcinoma (626 papers, 2014 to 2026). A carcinoma that arises from the lung and is characterized by the presence of malignant glandular epithelial cells. "For instance, we identified a myeloid cell-specific enhancer–promoter interaction for the CD274 gene (encoding programmed death-ligand 1 (PD-L1)) in lung adenocarcinoma (LUAD) sample TCGA-86-A4P8." (PMID 40355593, 2025). "MAPK is also shown to be associated with PD-L1 expression in lung adenocarcinoma, where inhibition of the MAPK pathway prevented the upregulation of PD-L1 protein and IFN-γ-induced CD274 mRNA." (PMID 36829496, 2023). "In this study, it was found that the CD274 high expression group had significant overlap with the highly expressed genes in lung adenocarcinoma patients (110 genes), and were enriched in cytokine-cytokine receptor interaction and IL-17 signaling pathway." (PMID 40568599, 2025). "Consistently, the regulation of CD274 expression by miR-155-5p has already been described in lung adenocarcinoma; however, the classification of miR-155-5p as an oncomiR or tsmiR remains controversial." (PMID 37409119, 2023). "Analysis of lung adenocarcinoma patient data set from TCGA revealed that IDO1 expression was positively correlated with CD274 and PDCD1LG2 expression." (PMID 37985999, 2023). "Consistently, analysis of the The Cancer Genome Atlas (TCGA) database revealed a positive correlation between ATXN3 and CD274 expression in human lung adenocarcinoma." (PMID 38038129, 2023). "Subsequently, we demonstrated the importance of MAPK signaling in the upregulation of PD‐L1 by growth factors and IFNγ in lung adenocarcinoma cell lines, which was mediated through CD274 mRNA stability and STAT1 activation." (PMID 30972766, 2019). "In the present study, we aimed to identify pathways regulating CD274 (PD‐L1) expression in this NSCLC subtype by using RNA sequencing data from The Cancer Genome Atlas (TCGA) lung adenocarcinoma and squamous cell lung carcinoma datasets." (PMID 30972766, 2019). "To investigate this hypothesis, we analyzed the expression of lipogenic genes, body mass index, and CD274 (PD-L1) levels from published multi-omics lung adenocarcinoma datasets." (PMID 39100092, 2024). "Using RNA immunoprecipitation followed by qPCR, the authors showed that NKX2-1-AS1 acts as a decoy to NKX2-1, preventing its binding to the CD274 promoter and thus negatively regulating endogenous PD-L1, limiting immune system evasion of lung adenocarcinoma cells." (PMID 37835376, 2023). "Importantly, the ratio of CD274-L2A to variant 1 was generally increased in cancer, as exemplified when comparing healthy lung to lung squamous cell carcinoma (LUSC) or lung adenocarcinoma (LUAD)." (PMID 31729316, 2019). "It is worth noting that there were only 9 intersections between the CD274-low expression group and the low-expression genes of lung adenocarcinoma, suggesting that the high expression of CD274 may be the dominant phenotype of immune escape in lung adenocarcinoma." (PMID 40568599, 2025). "Considering our discoveries that IL-1β prompts the upregulation of CD274 and PDCD1LG2 mRNA, as well as PD-L1 protein in lung adenocarcinoma cell lines, it is conceivable that heightened tumor or circulating IL-1β might additionally enhance the PD-1/PD-L1 axis’s suppression of cytotoxic T-cells." (PMID 37985999, 2023). "In the TCGA lung adenocarcinoma (LUAD, n=515) cohort, high expression of effector chemokines (CXCL10, CCL5) and mediators of STING pathway (TBK1, TMEM173) were associated with high levels of CD274 (PD-L1) and other targetable immune markers (LAG3, IDO1, PDCD1LG2, CTLA4)." (PMID 30400822, 2018). "In A549 lung adenocarcinoma cells, TGF-β1 induces PD-L1 expression via Smad2-dependent transcriptional activation of the CD274 gene." (PMID 40806457, 2025).
lung adenocarcinoma (continued). "In particular, expression level of CD274 gene showed AUC 0.67 for the whole NSCLC sampling, AUC 0.69 and 0.68 for the lung adenocarcinoma and squamous cell lung carcinoma subsets, respectively." (PMID 39723204, 2024). "A study of lung adenocarcinoma demonstrated that EML4-ALK fusion can upregulate p-STAT3 levels, then p-STAT3 upregulates PD-L1 expression by binding to the CD274 promoter." (PMID 38426097, 2024). "We were intrigued to see that the PD-1 ligands PD-L1(CD274 gene) and PD-L2 (PDCD1LG2 gene) mRNA were among top significant genes that were positively correlated with IDO1 mRNA in lung adenocarcinoma tumors." (PMID 37985999, 2023). "TCN1 is closely related to the molecular targets of lung adenocarcinoma BRAF, HHLA2, and CD274 (PD-L1), especially BRAF and HHLA2." (PMID 35287670, 2022). "Concomitant with our results it was previously reported that both EGF and IFNγ induce CD274 expression in lung adenocarcinoma cells and act through the MAPK cascade, and imbalanced PD-1/PD-L1 interaction is observed during viral infections." (PMID 34045585, 2021). "In a representative lung adenocarcinoma cell line panel, stimulation with EGF or IFNγ increased CD274 mRNA and PD‐L1 protein and membrane levels, which were further enhanced by combining EGF and IFNγ." (PMID 30972766, 2019). "In lung adenocarcinoma, it has been observed the existence of differential transcript expression for certain genes, such as the KRAS and the CD274 genes for which the expression levels of a number of their splicing isoforms appeared to be associated with disease initiation and progression." (PMID 38059347, 2024). "Finally, we found that COL11A1 is positively correlated with HAVCR2(TIM3), CD274 (PD-L1), CTLA4, and LAG3 in lung adenocarcinoma." (PMID 38649961, 2024). "Moreover, a blockade of the MAPK signaling cascade effectively thwarted the upregulation of CD274 mRNA and PD-L1 protein and membrane expression, instigated by EGFR and IFN-γ in lung adenocarcinoma cells." (PMID 38534769, 2024). "Finally, we found that the immune checkpoint genes CD274(PD-L1) and PDCD1LG2(PD-1) were also related to SPP1 in lung adenocarcinoma." (PMID 36688087, 2023). "Finally, we found that the immune checkpoint-related genes CD274(PD-L1) and PDCD1LG2(PD-1) was related to SPP1 in lung adenocarcinoma." (PMID 36688087, 2023). "Moreover, the SUMO-C1 group showed a higher expression of co-stimulatory and MHC molecules and lower expression of co-inhibitory molecules, such as CD274, PDCD1, and LAG3, which are now commonly used as immunotherapeutic checkpoints in lung adenocarcinoma." (PMID 37123398, 2023). "Research has shown that HCP5 promoted lung adenocarcinoma metastasis via the miR-203/SNAI axis and tumor growth and upregulated the expression of PD-L1/CD274 via a competing endogenous RNA mechanism of sponging miR-150–5p, and these were also consistent with our findings." (PMID 36147489, 2022). "Our TCGA analysis suggests that MAPK pathway activity and CD274 gene expression are primarily connected in lung adenocarcinoma, but not in squamous cell carcinoma of the lung." (PMID 30972766, 2019). "Thus, we analyzed the correlation between PD-L1 (CD274) and c-MET based on two TCGA datasets (Lung Adenocarcinoma, PanCancer Atlas, provisional)." (PMID 31747941, 2019). "This suggests that activation of the MAPK, PI3K/mTOR and IFNγ pathways is related to increased CD274 mRNA levels in lung adenocarcinomas without targetable genetic alterations." (PMID 30972766, 2019). "In this study we revealed a correlation between MAPK pathway activation and CD274 expression in lung adenocarcinomas without targetable genetic alterations using TCGA RNA sequencing data." (PMID 30972766, 2019). "Furthermore, examination of a TCGA lung adenocarcinoma cohort validated that PD-L1 (CD274) was positively correlated with YAP (YAP1), TAZ (WWTR1), and the YAP/TAZ signature, and NSCLC patients with high PD-L1 expression conferred poor survival probabilities." (PMID 34073318, 2021).
lung adenocarcinoma (continued). "Although CD274 transcription and MHC‐I‐related transcription are both regulated by STAT1 6, 35, MAPK inhibition, in contrast to JAK2 inhibition, does not affect MHC‐I expression, suggesting that MAPK activity primarily regulates CD274 mRNA stability in lung adenocarcinoma cells." (PMID 30972766, 2019). "Furthermore, back in 2002, language models were able to prioritise several oncogene targets of NSCLC, genes expressed in lung adenocarcinoma (LUAD) cell lines (see “Methods”, t-test with p-value 1e − 198) but not CD274." (PMID 37225853, 2023).
colon carcinoma (593 papers, 2013 to 2026). "CD274 expression was also increased in colonic tumor-associated eosinophils and metastasis-entrained eosinophils, which were both characterized by an IFN-γ signature." (PMID 34970274, 2021). "We selected immune checkpoints common in colon cancer therapy for analysis, finding that CD274, PDCD1, and HAVCR2 were positively correlated with the risk score." (PMID 34840571, 2021). "Moreover, our results showed that high infiltration of CD8+ TILs is positively correlated with the level of tumor CD274 either in MMR-proficient or MMR-deficient colon carcinoma patients." (PMID 30353144, 2018). "The results showed that PDCD1LG2, ICOS, CD86, CD80, CD48, and CD274 showed a significant exclusion situation from RFX1 expression in colon cancer." (PMID 41425715, 2025). "CD274 expressions in colon cancer cells HCT116, SW620, and RKO were higher compared with normal cells." (PMID 38166842, 2024). "We assessed tumor CD274 expression by immunohistochemistry and F. nucleatum DNA within tumor tissue by quantitative PCR in 812 cases among 4465 incident rectal and colon cancer cases that had occurred in two prospective cohort studies." (PMID 37538192, 2023). "We found that common checkpoints such as CD274, CEACAM1, HAVCR2, and CTLA4 in the treatment of colon cancer were significantly correlated with risk score." (PMID 34840571, 2021). "Specifically, colon cancer presented a different, double-peak pattern based on log-rank tests of CD274, and the bimodal distribution was also found in IDO1 expression by the TCGA cohort." (PMID 33425745, 2020). "We also noticed that the upregulation of IDO1 frequently co-occurred with the upregulation of PD-1, CD274 (also known as programmed death ligand 1, PD-L1), and cytotoxic T-lymphocyte-associated protein 4 (CTLA4) in colon cancer." (PMID 33425745, 2020). "In the present study, unsupervised hierarchical clustering analyses revealed that upregulation of immune-resistance markers, including PD-L1(CD274), was observed only in a subset of colon cancer from TCGA RNA-Seq data." (PMID 33425745, 2020). "We aim to clarify the relationships between CD8+ intratumor-infiltrating lymphocytes (TILs) and CD274 as well as their prognostic values in stage II-III colon carcinoma." (PMID 30353144, 2018). "We examined the expression levels of the CD274 protein in 867 cases of colon carcinoma treated at China Medical University Hospital in a retrospective cohort study." (PMID 30353144, 2018). "Here, we report that CD274 expression is positively correlated with CD8+ T cells infiltration and is associated with a favorable survival outcome in colon carcinoma." (PMID 30353144, 2018). "Notably, PRS exhibited a significant positive correlation with mRNA levels of immune checkpoint-associated molecules CD274, CTLA4, LAG3, and TIGIT in colon cancer tissues." (PMID 38577604, 2024). "Analysis of colon cancer cohort in TCGA database showed that APC mutation was associated with a lower TMB and was associated with a lower genes expression of PDCD1 (PD-1), CD274 (PD-L1) and PDCD1LG2 (PD-L2)." (PMID 36977982, 2023). "The expression of IDO1 in colon cancer in particular showed marked clustering with CD274." (PMID 33425745, 2020). "Hence, it is paramount to highlight that our gene expression results and the ones obtained from The Cancer Genome Atlas Program showed significantly lower levels of gene expression of PDL1 (CD274) in the AA colon tumors when compared to the CA cohort." (PMID 32983990, 2020). "Moreover, the density of CD8+ TILs was significantly correlated with the level of tumor CD274 in both MMR-proficient (p < 0.0001) and MMR-deficient (p = 0.0068) colon carcinoma patients." (PMID 30353144, 2018). "Subsequently, we examined whether the inclusion of other variables significantly associated with stage II–III colon carcinoma survival affected the parameter estimate for CD8+ TILs and tumor CD274." (PMID 30353144, 2018).
colon carcinoma (continued). "Notably, the expression of IDO1 in colon cancer showed marked clustering with CD274." (PMID 33425745, 2020). "The PRS exhibited a significant positive correlation with the infiltration of diverse immune cells, expression levels of related cytokines, and mRNA levels of immune checkpoints CD274, CTLA4, LAG3, and TIGIT in colon cancer tissues." (PMID 38577604, 2024). "The immune checkpoint molecules CD274, LAG3, and IDO1 expressions in tumor-infiltrating immune cells showed a better prognosis for patients with MSI-H colon cancer." (PMID 34993132, 2021). "The aim of this study was to analyze the interrelationship between tumor CD274, CD8+ TILs and microsatellite instability in a large cohort of patients with colon carcinoma and to evaluate its clinical relevance." (PMID 30353144, 2018). "In addition to SMC1A in the “hot” T‐cell inflammatory microenvironment of colon cancer, SMC1A also positively correlates with the immune checkpoint genes CD274, CTLA4, and PDCD1 in colon adenocarcinoma (COAD) samples." (PMID 37096492, 2023). "When the gene expression level of PD-L1 was analyzed, we also observed a positive correlation between CXCL9 expression and CD274 expression in our CRC cohort, which was supported by the data of colon cancer and rectal cancer cohort from TCGA." (PMID 36362062, 2022). "Aberrant expression of the programmed death-ligand 1 (PD-L1, also known as B7-H1 or CD274) checkpoint molecule has been reported in many cancers such as breast, lung and colon tumors as well as during chronic viral infections like those with Epstein-Barr virus (EBV) for example." (PMID 31382969, 2019). "In 867 cases of colon carcinoma, 384 patients (44%) had high tumor CD274 expression, 480 patients (56%) had low tumor CD274 expression and 4 patients had no results (tissues not available)." (PMID 30353144, 2018). "In the present study, we aimed to evaluate the relationship between CD274 expression and clinicopathological characteristics, including CD8+ cell density and microsatellite instability, and the prognosis of tumors harboring CD274 expression in a large cohort of resected colon carcinomas." (PMID 30353144, 2018). "Therefore, the CD8+ TILs counts and tumor CD274 may be prognostic factors to predict survival and therapeutic responses in stage II–III colon carcinoma patients." (PMID 30353144, 2018). "Therefore, as a consequence of this environment, CD274 and CD8+ TILs may be considered to be independent prognostic factors for colon carcinoma." (PMID 30353144, 2018). "Interestingly, in stage II–III colon carcinoma, a direct correlation between CD274 expression in tumor cells and CD8+ TILs was observed; 160 of 384 (41.9%) CD274-high tumors contained a high number of CD8+ TILs, and the remaining 223 (58.1%) CD274-high tumors had low CD8+ TILs." (PMID 30353144, 2018).
glioblastoma (545 papers, 2014 to 2026). The most malignant astrocytic tumor (WHO grade IV). "In glioblastoma, activation of β-catenin directly induces transcription of CD274 (encoding PD-L1) via β-catenin/LEF1 binding to the CD274 promoter, a process that is maintained by AKT signaling and is associated with reduced intratumoral CD8+ T cell accumulation." (PMID 41573582, 2025). "In both glioblastoma multiforme (GBM) and lower-grade glioma (LGG), ALPK1 showed a significant positive association with four immune checkpoints: PD-L1 (CD274), CTLA-4, LAG-3, and PD-1 (PDCD1)." (PMID 39845963, 2024). "Concomitantly, glioblastoma cells adapt to avoid detection and escape from the host immune system as highlighted by the reduced expression of CD274 during the morphological change in epithelioid phenotype." (PMID 36703629, 2022). "By contrast, it was demonstrated that β-catenin activation was able to induce β-catenin/TCF/LEF complex binding to the CD274 gene promoter and subsequently increase PD-L1 expression in glioblastoma." (PMID 36232859, 2022). "Further, we showed that these tumor-associated astrocytes were marked by JAK/STAT pathway activation and CD274 expression, which were confirmed in a set of de-novo and recurrent glioblastoma specimens." (PMID 31186414, 2019). "CD274 (PD-L1) facilitates immune escape in glioblastoma by inhibiting T-cell activity." (PMID 41179304, 2025). "Furthermore, HSChigh glioblastoma samples associated with the expression of immune checkpoint molecules, including PD-1 (PDCD1, p = 2.7 × 10−4), PD-L1 (CD274, p = 0.016), and PD-L2 (PDCD1LG2, p = 0.003)." (PMID 34162860, 2021). "We then performed immunohistochemical labelling on specimens from 43 glioblastoma patients with de-novo and recurrent glioblastoma to validate the presence of CD274+ astrocytes in the tumor environment, as well as GFAP and marker genes of various myeloid cell types." (PMID 31186414, 2019). "All cancers expressed CD274, with Ewings-sarcoma expressing the least and CLL (Glioblastoma multiforme) expressing the most." (PMID 38166842, 2024). "Our investigation revealed that glioblastomas with high RCD.GP scores highly expressed immune checkpoint genes, including CD274, CD247 and so on." (PMID 38378721, 2024). "According to the results, increasing CD274 expression in BLCA, BRCA, SKCM, and CESC negatively affects PFI but favorably affects GBM (glioblastoma multiforme) and LGG." (PMID 38166842, 2024). "It was also reported that the β-catenin/TCF/LEF complex binding to the CD274 gene promoter region induced by the Wnt ligand and activated EGFR promoted PD-L1 expression, which promotes glioblastoma immune evasion." (PMID 37759870, 2023). "There, genes with a higher expression in glioblastoma compared to astrocytoma were VEGFA, 4EBP1, CCL2, PLAU (uPA), CXCL8 (IL8), CXCL10 (IP10), CASP8, HGF, LIF, CD40, CDCp1, TNFRSF11B (OPG), CD274 (PD-L1), IL6, CXCL1, CCL20 (MIP3α), CCL8 (MCP2), CD244, MMP1, TNFRSF9, CXCL6, MMP10, FGF5)." (PMID 35301393, 2022). "In contrast to other cancers, however, we and others have demonstrated that the expression of PD-1 or its ligand PD-L1 (CD274, B7-H1) are not independent prognostic markers for glioblastoma patients and are relatively low in expression compared to other cancers." (PMID 40072074, 2025). "We conducted expression profiling of CD274 (PD-L1), GATA3, IFNG, IL12R, IL12RB2, IL4, PDCD1 (PD-1), PDCD1LG2 (PD-L2), and TBX21 (T-bet) using data of 158 glioblastoma multiforme (GBM) patients with clinical information available at The Cancer Genome Atlas." (PMID 29721184, 2018).